CA4 (carbonic anhydrase 4)
Diseases named in the same sentence as CA4 in open-access papers (continued):
Sharing a sentence is not in itself a finding about the gene and the disease.
cancer (continued). "CA-1 may have enhanced potency relative to CA-4 due to its anti-vascular effects but also due to its potential to induce cancer cell death via an ortho-quinone mechanism, binding to cellular nucleophiles and forming free radicles." (PMID 31947889, 2020). "Compound 13 showed the best cytotoxic activity in the HT-29 cell line in comparison to CA-4 (0.40 ± 0.05 μM vs 4.2 ± 0.5 μM); coefficient α calculated for this molecule was 80, which means significant selectivity towards cancer cells (coefficient α for CA-4–5.9)." (PMID 30875859, 2019). "The same derivatives were 8–24-fold more potent than CA-4 against HT29 cancer cell proliferation." (PMID 30141353, 2018). "The phenotypic response of cancer cells to CA4 treatment in vitro has been disruption of the microtubule network, prolonged mitotic arrest, mitochondrial depolarisation, release and activation of pro-apoptotic proteins, and, ultimately, cell death via apoptosis." (PMID 28253265, 2017). "Thus, it remains a distinct possibility that CA4 itself can induce apoptosis in cancer cells independently of microtubule targeting." (PMID 28253265, 2017). "Exploration of SARs based on IC50 values led to the identification of 5k as a prominent lead, which possessed remarkable antitumor potency against all the tested cancer cells with IC50 values ranging from 0.02 μM to 1.22 μM superior to references CA-4 and Crolibulin." (PMID 28240326, 2017). "CA-4 shows strong cytotoxicity against a variety of cancer cells, including MDR cell lines." (PMID 27754459, 2016). "Finally, considering the different effects that combretastatins might have on DNA damage in normal cells compared to cancer cells, we investigated the effects of CA-4 on DNA damage in PBMCs." (PMID 39766242, 2024). "However, considering we have validated significant prognostic implications of CA4 in KIRC, more investigative researches should be performed to further elucidate CA4 as potential biomarker for diagnosis, immunotherapy and prognosis in these cancers in the future." (PMID 32922550, 2020). "New perspectives in designs of novel multi-target agents against cancer may be developed on the basis of the recent studies of CA-4 hybrids with therapeutic agents, i.e., cyclooxygenase-2 inhibitors, ER ligands, HPAC inhibitors, and anticancer medications, cisplatin, and doxorubicin." (PMID 30875859, 2019). "The biological results for the furocoumarin analogs of CA-4 1, reported herein, shown that the structural modification of furocoumarins with the introduction of (Z)-styryl moiety may prove of great importance to obtain cytotoxic anti-cancer agents." (PMID 24962392, 2014). "Interestingly, (CA-4), a tubulin binding agent best known as a vascular disrupting drug and currently in clinical development for ovarian and anaplastic thyroid cancers, is one of only few compounds known to induce RhoA kinase activity in the cancer vasculature." (PMID 40140727, 2025). "The TF-protein NFKB1 (a regulator of GUCA2A, CA4, CEMIP and MS4A12) is a suppressor of inflammation, ageing and cancer." (PMID 36991484, 2023). "Carbonic anhydrases, particularly CA4 and CA7, have been suggested to play important roles in extracellular acidification in cancer." (PMID 35787947, 2023). "In another study, the linker of CA-4 was replaced with selenide, and st.2 was active at nM concentration against MCF-7 cancer cell lines." (PMID 36551271, 2022). "CA-4’s potential as an anti-cancer agent has long since been recognised, and it demonstrates potent cytotoxicity against MDR cancer cell lines." (PMID 31947889, 2020). "Biphenyl analogues of CA4, MP5-F9 and MP5-G9, were also evaluated and were determined to have a similar ability to inhibit cancer proliferation." (PMID 28253265, 2017).
cancer (continued). "In the past several decades, CA4 has been found to be a potent microtubule targeting agent (MTA) and capable of drastically inhibiting cancer cell proliferation in vitro." (PMID 28253265, 2017). "Compound 6i showed the most highly active antiproliferative activity against the three human cancer cell lines with an IC50 values of 0.011–0.015 μM, which are comparable to those of CA-4 (IC50 = 0.009–0.013 μM)." (PMID 28931885, 2017). "Consequently, these triazole analogues of CA-4 could serve as promising alternatives to the natural product, although further studies about their biological activity are essential in order to fully determine their viability as therapeutic agents in the treatment of cancer." (PMID 39860187, 2025). "However, in this series, compound St.7 was one of the most potent compounds against MCF-7 cancer cell lines with IC50 values in the nanomolar level, and it showed the inhibition of tubulin polymerization with IC50 1.3 μM in comparison with CA-4 IC50 1.2 μM." (PMID 36551271, 2022). "CA-4 has a potent cytotoxic effect against many human cancer cell lines including multidrug resistance (MDR) cancer cells in vitro while not in vivo due to its low solubility and the instability of its cis configuration." (PMID 32486408, 2020). "The synthetic benzophenone phenstatin 3a and phosphate prodrug 3b show potent cytotoxic activity in cancer cells together with microtubule-destabilising activity, while the isoCombretastatin 3c, a stable non-natural isomer of CA-4, shows equivalent anti-cancer properties to CA-4." (PMID 34832901, 2021). "They note that while non-isomerizable analogues of CA-4 may display more potent anti-cancer activity, there still remains issues with drug specificity." (PMID 31947889, 2020). "In addition to the cancer cell lines tested, various non-cancerous equivalents were utilized to evaluate the selectivity of CA4 and its analogues." (PMID 28253265, 2017). "This hypothesis is supported by the observation that multiple analogues of CA4 have been found to retain anti-cancer activity that is seemingly independent of microtubule inhibitory activity." (PMID 28253265, 2017). "Despite significant advances in drug discovery and the promising antitumor potential of combretastatin A4 (CA-4), which selectively targets rapidly dividing cancer cells, CA-4’s effects on non-dividing human cells, such as peripheral blood mononuclear cells (PBMCs), remain unclear." (PMID 39766242, 2024). "Of the 201 downregulated genes, 125 were identified in the previous study (GEO results) and only 76, such as cysteine rich domain 2 (STAC2), BTNL9, CA4, GPIHBP1 and PIGR, had not been studied on any cancer." (PMID 31182966, 2019). "Although apoptosis inducing factor (AIF) has been shown to be released from mitochondria following CA4 treatment, inhibition of poly (ADP-ribose) polymerase (PARP), which is necessary for AIF nuclear translocation, fails to rescue cancer cells from dying." (PMID 28253265, 2017).
infection (21 papers, 2016 to 2026). The state of being infected such as from the introduction of a foreign agent such as serum, vaccine, antigenic substance or organism. "In this population, ion transporters including Slc26a3 and Ca4 were downregulated post-infection, indicating that infected enterocytes sensed C. rodentium and altered their gene expression profile." (PMID 41361166, 2025). "Nevertheless, considering the expected high micromolar concentrations of cA4 in the cell upon infection we believe that cA4 is the preferred ligand of Csa3Sso." (PMID 35038453, 2022). "The lack of titration of Csx1 activity observed here is due to its high affinity for cA4, resulting in full activation even at very low simulated infection levels." (PMID 32338598, 2020). "These viral ring nucleases can abrogate type III CRISPR immunity by rapidly destroying the cA4 infection signal." (PMID 32597755, 2020). "This could suggest that RNs targeting molecules other than cA4 simply await discovery, or alternatively that infection outcomes are different in these cases." (PMID 40904116, 2025). "Although this conclusion may be influenced by a sampling bias, it appears that cA4 is the default cyclic nucleotide employed to signal infection and activate defences in type III CRISPR systems." (PMID 32597755, 2020). "The cA4 binding affinities and activities of the two constituent enzymes in the fusion protein may have evolved to ensure a robust but time-limited cOA-activated ribonuclease activity that is finely tuned to cA4 levels as a second messenger of infection." (PMID 32347937, 2020). "Thus, the kinetic modelling demonstrated that addition of a ring nuclease activity allows the cell to respond differently to varied levels of infection, and therefore cA4 concentration, resulting in a range of RNA degradation levels." (PMID 32338598, 2020). "To model the generation of cA4 by the Csm:target RNA complex, we set the concentration of that complex at 6, 60 or 600 μM (equivalent to low, medium and high levels of infection), allowing the generation of the equivalent concentration of cA4 with the measured rate constant of 0.04 min−1." (PMID 32338598, 2020). "The interaction term (PC NCFxG) revealed to be the most strongly correlated with the neurobehavioral outcomes, indicating the interactions between genotypes (COMT, BDNF) and neonatal factors (infection, invasive procedures, surgery, GA), which were mainly loaded on CA4/DG and alveus." (PMID 30941021, 2019). "Notably, at the highest simulated infection level of 600 μM cA4, Csx1 persists in a 100% activated form for over 1200 min in the absence of AcrIII-1, but is reduced to 50% activated within 150 min in its presence, with similar effects seen at lower cA4 concentrations." (PMID 32338598, 2020). "Interestingly, immunization with CA4-DelNS1 virus and ca-LAIV also protected against a H7N9 virus challenge with 10 50% murine lethal doses (MLD50), with mice displaying only slight body weight loss during the first 3 days of infection, followed by full recovery." (PMID 31530680, 2019). "The cA4 second message then activates Csa3a, inducing expression of the acquisition genes, the uptake and expression of new spacers, and their incorporation into both type I-A and type III surveillance complexes, which are then able to cure the infection." (PMID 34944496, 2021).
bacterial infection (2 papers, 2024). "AHR deficiency in intestinal epithelial cells has been linked to increased susceptibility to pathogenic bacterial infection because of reduced expression of Muc2 and carbonic anhydrase 4 (Car4)." (PMID 39589551, 2024).
cardiovascular disease (1 paper, 2024). "Studies investigating activity and expression of carbonic anhydrases in cardiovascular disease have found elevated CA1 and CA2 expression in diabetic ischemic cardiomyopathy as well as elevated expression of CA2 and CA4 in patients with hypertrophic hearts." (PMID 38500750, 2024).
neuromuscular disease (1 paper, 2018). "Recently, it has been shown that inhibition of CA4 effects relaxation of skeletal muscles both in model organisms and human cells, suggesting their importance as potential drug targets in neuromuscular diseases." (PMID 30050560, 2018).
CA4 also shares sentences with these, for which no sentence is quoted: heart failure (4 papers); influenza (4); colitis (3); melanoma (3); renal cell carcinoma (3); thyroid cancer (3); asthma (2); bladder urothelial carcinoma (2); colon adenocarcinoma (2); esophageal carcinoma (2); head and neck squamous cell carcinoma (2); hepatocellular carcinoma (2); inflammation (2); liver cancer (2); lung squamous cell carcinoma (2); non-small cell lung carcinoma (2); Obesity (2); ovarian adenocarcinoma (2); rheumatoid arthritis (2); schizophrenia (2); uveal melanoma (2); acute myeloid leukemia (1); Allergy (1); anaplastic astrocytoma (1); anemia (1); autoimmune pancreatitis (1); autosomal dominant retinitis pigmentosa (1); B-cell acute lymphoblastic leukemia (1); B-cell lymphoma (1); breast adenocarcinoma (1).
A further 51 diseases each share a sentence with CA4 in 1 paper.